BST2 (bone marrow stromal cell antigen 2)
Diseases named in the same sentence as BST2 in open-access papers (continued):
Sharing a sentence is not in itself a finding about the gene and the disease.
tumor (continued). "BST-2 expression was significantly higher in tumor tissues compared to their paired normal breast tissues." (PMID 25499888, 2014). "The striking effects of BST-2 on tumor growth and metastasis led us to define the cellular basis for BST-2 effect on breast tumorigenesis." (PMID 25499888, 2014). "Separation of the data into low, intermediate, and high BST-2 levels showed that subjects whose tumors had high BST-2 had strikingly larger tumors compared to the tumor masses in subjects with intermediate and low BST-2." (PMID 25499888, 2014). "BST-2 is a unique innate immunity gene with both antiviral and pro-tumor functions and therefore can serve as a paradigm for understanding the roles of other innate immunity genes in cancers." (PMID 25499888, 2014). "BST-2-expressing E0771 cells (shControl) showed significant decrease in tumor latency compared to BST-2-suppressed E0771 cells (sh413)." (PMID 25499888, 2014). "In vivo, we examined the effect of knockdown of BST-2 in two different murine carcinoma cells on tumor growth, metastasis, and survival." (PMID 25499888, 2014). "BST2 immunolocalization in tissue arrays was verified in full-sized sections of tumor tissue blocks in several cases." (PMID 23840623, 2013). "We describe approaches and consequences of in vitro manipulation of BST2 towards the overall goal of suppressing functional hallmarks of tumor aggressiveness." (PMID 23840623, 2013). "Overexpressing tumor cultures treated with increasing doses of resveratrol for 24 hr demonstrated a significant reduction in BST2 transcript levels (p<0.01)." (PMID 23840623, 2013). "Our data suggests that impaired TGFβ signaling leads to the inability of AP2 to bind the BST2 promoter resulting in failed repression of this putative oncogene in high grade tumor cells." (PMID 23840623, 2013). "Closely analogous to the consequences of BST2 knockdown on the cell cycle, resveratrol treatment of tumor cultures induced a marked decline in S-phase cells accompanied by an increase in the G1 fraction." (PMID 23840623, 2013). "Binding of the transcription factor AP2 to the BST2 promoter was attenuated by inhibition of the TGFβ pathway thereby increasing BST2 expression in tumor cells." (PMID 23840623, 2013). "Using Martingale residuals as a measure of the influence of BST2 expression on the hazard ratio in a Cox Proportional hazards model, an increasing hazard ratio was noted for 55 cases where BST2 expression in the tumor ranged between 7.0 to 9.5 units." (PMID 23840623, 2013). "The BST2 expression has been identified in multiple myeloma and involved in the tumor invasion and progression." (PMID 19338666, 2009). "In HNSCC, the overexpression of BST2 may enhance tumour cell survival by activating the AKT/ERK1/2 pathway and is linked to immune evasion." (PMID 40475773, 2025). "This integrated analysis, linking immune modulation with neuromimicry, offers a novel framework for understanding how BST2 engineers a complex ecosystem conducive to tumor growth, invasion, and immune evasion, thereby positioning it as a compelling therapeutic target." (PMID 41281378, 2025). "Crucially, BST2 overexpression also drove M2 macrophage polarization within the EOC tumor tissue." (PMID 41281378, 2025). "Additionally, among the upregulated genes, we identified genes that have increased expression in metastatic cancer cells, such as the BST2 gene, or promote cancer cell migration, tumor growth, and angiogenesis like IFI27." (PMID 39405604, 2024). "These pieces of evidence strongly suggest that the interaction of BST2 with ILT7 may contribute to tumor immune suppression and pDC–tumor crosstalk." (PMID 38504978, 2024). "BST2 was one of the proteins that were found to be related to tumor metastasis." (PMID 37033258, 2023). "In vivo experiments demonstrated that knocking down BST2 expression could significantly inhibit the proliferation of CRC while overexpression of BST2 enhanced tumor progression." (PMID 36594082, 2023).
tumor (continued). "In vitro experiments further demonstrated that downregulated BST2 expression could significantly inhibit tumor proliferation and migration." (PMID 36594082, 2023). "Nonetheless, macrophage amplification in LNs—for instance, via an induction of podoplanin expression in LECs or via blockade of CD200 or BST2—could help to activate endogenous as well as vaccine-induced tumor immunity." (PMID 35892863, 2022). "This hints at the possibility of BST2 regulating viral protein expression and may uncover the role of BST2 in other physiological conditions, such as tumor development." (PMID 36176574, 2022). "Furthermore, BST2 activates the nuclear factor-κB-Snail-Raf kinase inhibitor protein axis to promote tumour invasion and metastasis via EMT." (PMID 35968507, 2022). "This suggests that BST2 expression may represent a marker of anti-tumor macrophages in the PDAC microenvironment." (PMID 35316682, 2022). "Interestingly, BST2 upregulation in fLECs was already detectable by immunofluorescence staining at day 6 after tumor implantation, whereas tenascin was only induced at late stages, suggesting varying kinetics of tumor-induced responses by fLECs." (PMID 35892863, 2022). "It has been indicated that decreased BST2 expression can inhibit tumor cell proliferation." (PMID 35864225, 2022). "Recent reports implicate BST2 elicits its pro-tumor effects through the formation of BST2 dimers." (PMID 33922087, 2021). "In particular, IL6 and BST2 were significantly induced in all naïve MSCs after 3 days’ coculture with primary tumor cells, whereas the expressions of ADAMTS12, MX2, LOXL2 and GREM1 varied and displayed transient induction during the course of the coculture assay." (PMID 34513701, 2021). "While the higher EC50 of B18L for erythrocytes may stem from the hydrophobic nature of their membranes compared to cancer cells, the higher IC50 for PBMCs may be the result of low BST-2 protein on the surface of PBMCs compared to tumor cells." (PMID 32872253, 2020). "Correlation of BST-2 expression and tumor aggressiveness was analyzed in human tissue samples." (PMID 30514852, 2018). "Furthermore, we demonstrate that restoration of the ECD cysteine residues is sufficient to rescue cell survival and tumor growth via a previously unreported pathway—BST-2/GRB2/ERK/BIM/Cas3." (PMID 28300825, 2017). "Together, these data suggest that disruption of BST-2 dimerization may serve to prevent tumor growth and metastatic colonization of the lungs, thus increasing overall survival of tumor-bearing hosts." (PMID 28300825, 2017). "Taken together, these observations suggest that the exosome-based secretion pathway may represent one of the potential mechanisms for shedding of BST2 into blood circulation from CRC tumor cells." (PMID 26494939, 2015). "Comparison of BST-2 expression levels in the different stages within the different subtypes show significant disease stage-dependent differences in BST-2 mRNA in the luminal tumor types compared to normal breast tissue." (PMID 25860442, 2015). "Although our data showed the significant elevation of tissue and plasma BST2 levels in CRC patients compared to normal controls, how BST2, a type II transmembrane protein, can be released from tumor tissue into the blood circulation remains unclear at present." (PMID 26494939, 2015). "In addition to increased tumor growth at the primary and secondary sites, mice bearing BST-2-expressing 4T1 shControl cells developed malignant ascites and splenomegaly or ascites and shock in the case of E0771 shControl cells-bearing mice." (PMID 25499888, 2014). "Whether the decrease in metastasis observed in mice bearing tumors from BST-2 suppressed cells is a direct result of reduced tumor size or delayed metastasis is unknown." (PMID 25499888, 2014). "Furthermore, Kaplan-Meier model showed that subjects with high tumor BST-2 had significantly reduced survival than those whose tumors had low BST-2 expression." (PMID 25499888, 2014).
tumor (continued). "The results of this study as summarized in our model reveal the critical role of BST-2 in the many processes involved in mammary oncogenesis by showing that BST-2 expressed in carcinoma cells is a positive disease modifier and elevated levels of BST-2 predict tumor aggressiveness and host survival." (PMID 25499888, 2014). "The effect of BST-2 in tumor development was also evident in the E0771-C57BL/6 model." (PMID 25499888, 2014). "We found that, BST-2 expression increased with tumor aggressiveness in human patients." (PMID 25499888, 2014). "In both 2-dimensional and 3-dimensional growth conditions, BST2-silenced tumor cells displayed an enhancement in tamoxifen or staurosporine-induced apoptotic cell death together with a reduction in the S-phase fraction compared to BST2 overexpressing counterparts." (PMID 23840623, 2013). "The tumor sample was classified as BST2 deficient as it was negatively stained (absence of brown indicates reduced expression)." (PMID 19338666, 2009). "Therefore, identifying tumor-intrinsic factors, such as BST2, that may orchestrate this immunosuppressive axis is a key objective of this investigation." (PMID 41281378, 2025). "Furthermore, NF-κB pathway seemed to be involved in the pro-tumour function of BST2." (PMID 33810350, 2021). "The interaction between BST-2-expressing primary tumor cells and other resident stromal cells may regulate the expression of other factors in secondary organs, thus conditioning metastatic sites for subsequent arrival of tumor cells, especially tumor cells that express dimeric BST-2." (PMID 28300825, 2017). "To test whether the reduced metastasis observed in mice bearing tumors from BST-2-suppressed cells reflect a delay in metastasis due to delayed primary tumor growth and differences in tumor size, we performed a linear regression analysis for correlation between primary tumors and metastatic growth." (PMID 25499888, 2014). "Our in vivo study revealed that expression of BST-2 may promote tumor growth at secondary sites." (PMID 25499888, 2014). "However, elevated levels of BST-2 in cancer cells have pro-tumor functions." (PMID 25499888, 2014). "In contrast, BST-2 expression was significantly higher in epithelial cells from tumor compared to epithelial cells from normal breast tissues.These data suggest that epithelial cell-intrinsic BST-2 may be a significant contributor of elevated BST-2 in tumor tissues." (PMID 25499888, 2014). "Therefore, BST-2 upregulation may be an important step in a series of changes that tumor cells undergo during transformation." (PMID 25499888, 2014). "However, the functional consequence of BST-2 expression in tumor tissues and cells is completely unknown and there has been no direct demonstration of the involvement of BST-2 in breast tumorigenesis." (PMID 25499888, 2014). "However, BST-2 expression between stromal cells (tumors versus normal breast tissues) was not different, indicating that tumor epithelial cells could partly be contributory to elevated BST-2 in tumor tissues." (PMID 25499888, 2014). "Crucially, within the EOC context, the transcription of BST2 is directly regulated by CFP1, linking it to tumor cell proliferation and apoptosis inhibition." (PMID 41281378, 2025). "Ovalbumin (OVA) immunization in combination with anti-BST2 antibodies and poly(I:C) has been shown to enhance adaptive immunity, thereby improving B16-OVA tumor rejection." (PMID 39796009, 2024). "Post-treatment tumors also exhibited a significant downregulation of tumor antigens (MAGEA3, BST2) when compared to baseline." (PMID 39506856, 2024). "Tumour cells showed clear separation of Kmt2c and Kmt2d KO from WT, and differential gene expression (DGE) analysis identified Ly6a, Bst2, Ifi27l2a and Stat1 as the top highly upregulated genes in both KO tumour cells compared with the WT." (PMID 38926506, 2024).
tumor (continued). "In NPC, overexpression of BST2 inhibits the endogenous replication of EBV and increases tumor cell resistance to cisplatin, indicators of poor outcomes." (PMID 38753689, 2024). "The core TAM2-driven genes, including BCAT1, BST2, and MERTK, are involved in regulating tumor progression and TAM2 polarization, which are potential targets for PC therapy." (PMID 37628967, 2023). "Specifically, the BST2 gene signature predicted a response to a CTLA4 antibody called ipilimumab, suggesting a mechanistic involvement in tumor progression." (PMID 37414767, 2023). "Furthermore, a number of interferon (IFN) response genes (BST2, CD74, HLA-DMA, HLA-DPB1, HLA-DQB1, HLA-DRA, HLA-DRB1, and IRF8) were upregulated in C10 compared to the other clusters, whereas genes associated with tumor suppression and apoptosis (TFF1 and TFF2) were downregulated." (PMID 37370788, 2023). "The expression of NOG and S1PR1 genes was also increased in CFP1-deleted tumor tissue cells, while the expression of RASSF9 and BST2 was decreased significantly." (PMID 35864225, 2022). "Finally, a series of experiments confirmed that the expression of BST2 can be significantly increased by IFN induction, and knockdown of BST2 can significantly inhibit the growth and invasion of GBM cells, and may affect the phenotype of tumor-associated macrophages." (PMID 35865015, 2022). "The interferon gamma-related gene BST2 emerged as a DEG that was highly expressed in GBM and negatively correlated with tumor purity." (PMID 35865015, 2022). "Five aberrantly methylated genes (epidermal growth factor, EGF; carbohydrate sulfotransferase 10, CHST10; ependymin related 1, EPDR1; bone marrow stromal antigen 2, BST2; and Rac family small GTPase 3, RAC3) were further verified in CRC tumor tissues." (PMID 30360391, 2018). "Thus, we investigated whether BST-2 enhances the metastatic potential of primary tumor cells." (PMID 25499888, 2014). "In contrast to these effects, treatment of 2 independent grade 1 tumor cell lines with the TGFβ inhibitor - SB431542, induced up to 2-fold increase in BST2 (p<0.01)." (PMID 23840623, 2013). "BST2 positive primary tumors with a concurrent DCIS component were found to display strong staining in both pre invasive and invasive tumor cells." (PMID 23840623, 2013). "Consistent with our statistical analysis, quantitative PCR confirmed the upregulation of BST2 and MFAP2 and the downregulation of KRT31 when samples of HNSCC were compared to tumor-free surgical margins." (PMID 19014460, 2008). "The observed in vivo phenotypes likely represent a composite effect, as BST2 is expressed in both tumor and nontumor cells within the TME; future work using cell-type-specific models is required to dissect these distinct contributions." (PMID 41281378, 2025). "Specifically, BST2 expression was upregulated in these tumor tissues compared to adjacent non-tumorous tissues." (PMID 37389178, 2023). "The absence of BST2 on NK cells can enhance their cytotoxicity against tumor cells compared to wild type NK cells." (PMID 36232695, 2022). "The antiviral protein BST2 and the extracellular matrix protein tenascin were again broadly expressed by all three LEC subsets, but nonetheless showed the strongest elevation in fLECs in tumor-draining LNs." (PMID 35892863, 2022). "Moreover, Nutlin also regulated the tumor-promoting HSF1 targets CDC6, ITGB3BP, RBBP5, BST2, and FBLN1." (PMID 34188043, 2021). "Owing to an upregulation of interferon-inducible genes, including Ifit1, Ifit3 and Bst2, the EO771 and EO771.LMB tumours might correspond more closely to the interferon-rich subtype of human basal-like tumours." (PMID 25633981, 2015). "We found that BST-2 is hypomethylated on the CpG sites represented by probes 3 to 9 irrespective of tumor subtype." (PMID 25860442, 2015). "One of the drivers of breast malignancy is BST-2, also known as Tetherin, CD317, or HM1.24." (PMID 25860442, 2015).
tumor (continued). "Examples of tumor-related overexpressed genes which become promoter hypomethylated during carcinogenesis includes, but not limited to, Sonic Hedgehog, P-cadherin, and CDH3, as well as MATN4 and CTSL2, supporting the data reported here for BST-2." (PMID 25860442, 2015). "Strong AP2 binding to the BST2 promoter was observed in 5/5 grade 1 & 2 tumor cell lines whereas no binding was detected in 2/2 grade 3 lines, and in MCF7 cells." (PMID 23840623, 2013). "Exposure of grade 1 & 2 tumor cell lines to TGFβ for 24 hr resulted in further suppression of BST2 transcripts whereas no change was observed in grade 3 cell lines by QPCR analysis, suggesting transcriptional regulation of BST2 in TGFβ responsive tumor cells." (PMID 23840623, 2013). "Grade 3 tumor cell lines expressed abundant BST2 protein, whereas considerably lower or no protein expression was observed in grade 1 & 2 cell lines." (PMID 23840623, 2013). "These correlation analyses further supported that MHC-II+/BST2+ Macrophages, CD43−IgD+ mature B cells, and cDCs might contribute to anti-tumor immunity, whereas Arg-1+ Macrophages, CD43+IgD− immature B cells, MDSCs, and Tregs may have immunosuppressive effects in PDAC." (PMID 35316682, 2022). "Whether BST2, similarly to E-selectin, might facilitate adhesion not only to monocytes but also to tumor cells has to be clarified in further studies." (PMID 31963450, 2020). "As the interaction between BST‐2 and ILT7 suppress pDCs‐mediated IFN responses required for deterring tumor growth 151, 152, it is tempting to speculate that elevated BST‐2 in tumors 119, 131, 153 and engagement of ILT7 by BST‐2 may contribute to tumor tolerance and progression." (PMID 27042298, 2016). "However, our in vitro studies that showed that cells with suppressed BST-2 have reduced adhesion, anchorage-independent growth, migration, and invasion supports a role for BST-2 in promoting tumor growth at distal sites, because these cancer cell behaviors are critical for metastasis." (PMID 25499888, 2014). "However, no studies have analysed the expression of the BST2 gene in sCRC tumours." (PMID 36077612, 2022). "In addition, the lack of correlation between formation of primary tumor and lung or intestinal/mesentery colonization in our mouse model suggests that BST-2 may differentially promote tumor growth at the primary and secondary sites." (PMID 25499888, 2014). "Addition of TGF-β to tumor cell-N-MSC co-culture augmented MX2, BST2 and IL6 (right columns) but not ADAMTS12, LOXL2 GREM1 or CHI3L1 expression in N-MSCs." (PMID 29503225, 2018). "Bone marrow stromal cell antigen 2 (BST2) or CD317, playing a crucial role in antiretroviral defence in innate immune response, is also overexpressed in GC tissues compared to contiguous non-tumorous tissue and is correlated to tumour stage and lymphatic metastasis." (PMID 33810350, 2021).